CIMIP7 (ciliary microtubule inner protein 7)
Synonyms: C3orf84
Tractability: No criterion of Open Targets' tractability assessment is met for any kind of drug.
Gene: Protein-coding gene on chromosome 3 (49,177,634 to 49,191,858, reverse strand). Ensembl gene ENSG00000236980.
Subcellular location: Cell projection, cilium
Gene Ontology:
Cellular component: cilium
Genetic constraint (gnomAD): Loss-of-function variants: 14 observed, 15.05 expected, observed/expected ratio (o/e) 0.93, 90% interval 0.61 to 1.45. The upper end of that interval is the gene's LOEUF score, 1.45, which puts it in group 6 of 6, group 1 being the genes least tolerant of losing a copy. Missense variants: 222 observed, 255.16 expected, observed/expected ratio (o/e) 0.87, 90% interval 0.78 to 0.97. Synonymous variants: 106 observed, 102.58 expected, observed/expected ratio (o/e) 1.03, 90% interval 0.88 to 1.21.
Homologues: Orthologues: chimpanzee C3H3orf84 (97% identical), macaque C2H3orf84 (95% identical), rabbit CIMIP7 (82% identical), pig CIMIP7 (82% identical), dog CIMIP7 (80% identical), mouse BC048562 (78% identical), guinea pig CIMIP7 (75% identical), tropical clawed frog c4h3orf84 (32% identical).